MTOR (mechanistic target of rapamycin kinase)
Diseases named in the same sentence as MTOR in open-access papers (continued):
Sharing a sentence is not in itself a finding about the gene and the disease.
cancer (continued). "We also found that changes in SNV, the mTOR pathway gene, were also predominant in most cancers." (PMID 34194607, 2021). "Temsirolimus is a mTOR inhibitor used for the treatment of various forms of cancer." (PMID 34452154, 2021). "In addition, the mTOR signaling pathway exists widely and controls the proliferation and metabolism of cancer cells." (PMID 34790582, 2021). "The PI3K/AKT/mTOR signaling pathway is an effective therapeutic target in PTEN-deficient cancer cells, but its inhibitors can induce resistance via feedback activation of STAT3, which provides an empirical basis for combining both PI3K/AKT/mTOR and STAT3 inhibitors." (PMID 33431808, 2021). "The current study revealed that eIF6-related signaling pathways activated in HCC were enriched in ribosome biogenesis, cell cycle and mTOR-related cancer signaling pathway, which may stimulate tumor proliferation and invasion." (PMID 34016142, 2021). "Notably, KRAS mutant cancer cells have been shown to develop anticancer drug resistance through hyperactivation of mTOR signaling." (PMID 34003553, 2021). "In addition to its role as intracellular antioxidant similar to cancer cells, glutathione in T-cells also supports mTOR and NFAT activation, thus driving glycolysis and glutaminolysis and promoting inflammatory responses." (PMID 35070990, 2021). "Additionally, the progression and metastatic potential and the preference of metastatic sites were analyzed in correlation with mTOR hyperactivity in different cancers." (PMID 35029792, 2021). "Hyperactivation of mechanistic target of rapamycin (mTOR) signaling pathway is involved in the regulation of cellular growth, proliferation, and more in general, is a common phenomenon in most types of cancers." (PMID 34044827, 2021). "Indeed, CyPA was found to inhibit oxidative stress and apoptosis by modulating the PI3K/Akt/mTOR signaling pathway in cancer cells." (PMID 33809359, 2021). "The phosphatidylinositol 3-kinase/protein kinase-B/mammalian target of rapamycin (PI3K/Akt/mTOR) signaling cascade is one of crucial pathways which is aberrantly activated in many cancers, resulting in certain disturbances in the regulation of cell proliferation and various cellular processes." (PMID 34507160, 2021). "In addition, mTOR seems to play an important role in cancer occurrence, development, and chemotherapy." (PMID 34869595, 2021). "So far, most attempts by using mTOR/Akt inhibitors focus on cancers." (PMID 33828998, 2021). "Additionally, mTOR has a key function in the proliferation, angiogenesis, and migration of cancer cells." (PMID 34452154, 2021). "We found that these genes are implicated in signaling pathways commonly upregulated in cancer (Wnt, MAPK, BMP, mTOR, NOTCH, PI3K/Akt), in DNA replication, recombination and repair, cell junction, actin cytoskeleton, regulation of transcription, and calcium ion transmembrane transport." (PMID 34439480, 2021). "mTOR inhibitors and immunotherapies in preclinical cancer models." (PMID 33802831, 2021). "Therefore, inhibition of TCP1 occurred via decrease of p-AKT in the PI3K/AKT/mTOR pathway to inhibit the development of OC, which was a central regulator of metabolism, survival, and proliferation in normal and cancer tissues." (PMID 34162426, 2021). "Indeed, we showed that the combined action of inhibitors of the mTOR pathway with N6L synergistically inhibited the cancer cells’ proliferation." (PMID 34638443, 2021). "Importantly, mTOR also plays a critical role in modulating the balance between life and death of a cancer cell." (PMID 34283054, 2021). "Increased infiltrating macrophages were associated with increased renal cell carcinoma cells invasion capabilities and metastasis via inducing the epithelial-mesenchymal transition (EMT) and increased cancer stem cell-like populations by activating the Akt and mTOR signaling pathway." (PMID 35250965, 2021).
cancer (continued). "pS6, the active form of the effector S6 for PI3K/mTOR signaling, and phosho-ERK (pERK), the active form of the effector ERK for mitogen-activated protein kinase (MAPK) signaling, are upregulated in HPV-associated cancers according to previous reports." (PMID 34068608, 2021). "However, the central role of PI3K/AKT/mTOR signaling varies among diverse biological processes, suggesting the need for more specific and sophisticated strategies for their use in cancer therapy." (PMID 34298731, 2021). "NO has been shown to participate in a variety of signaling pathways, including Ras, extracellular signal-regulated kinases (ERK), protein kinase B (Akt), cyclin D1/retinoblastoma (Rb), and the mammalian target of rapamycin (mTOR), which are essential for cancer cells." (PMID 34199647, 2021). "In addition, mTOR is frequently hyperactivated in cancer, and mTORC1 has often been observed to be deregulated in a wide variety of human cancers." (PMID 33037985, 2021). "The mTOR inhibitor effects as cancer monotherapy have been limited, perhaps because they only exhibit poor proapoptotic activity, being mainly cytostatic and because of the existence of a negative feedback loop on PI3K/Akt, resulting in enhanced PI3K/Akt upon mTOR inhibition." (PMID 34500781, 2021). "Perhaps this activity may be leveraged to develop a combination therapy by combining miRNA-99a-5p and the mTOR inhibitor TSC in other cancers." (PMID 34262466, 2021). "AKT/mTOR signaling plays a key role in promoting malignant processes of cancers." (PMID 34007784, 2021). "However, higher mTOR activity was described in many various cancers; the in situ staining pattern (heterogeneity) and the mTORC1/C2 complex distribution were not studied in detail." (PMID 35029792, 2021). "In addition, novel analogs of PL and their interaction with this pathway can be explored, which would help to develop novel Akt/mTOR inhibitors for the treatment of different cancers." (PMID 36046754, 2021). "Therefore, in this part of study, we concluded that eIF6 activated mTOR-related multiple cancer signaling pathways to promote the malignant progression of human HCC." (PMID 34016142, 2021). "The mTOR inhibitor Afinitor (everolimus) was approved in 2012 for metastatic HR-positive/HER-negative breast cancer in combination with an AI exemestane in patients whose cancer had progressed despite treatment with letrozole or anastrozole." (PMID 33670524, 2021). "Studies have reported that combination therapy of SAR405 with the mTOR inhibitor everolimus promotes the inhibition of cancer progression in renal tumour cell lines, hence indicating the efficacy of SAR405 as an anticancer drug that targets the regulation of autophagy." (PMID 33802014, 2021). "The sensitivity to mTOR inhibition by rapamycin may vary by several orders of exposure, indicating an intrinsic resistance to mTOR inhibition in different cancer types." (PMID 33918290, 2021). "Moreover, it is well known that mTOR is upregulated in KRAS mutant cancers, but KRAS can directly turn on the self-digestive process, keeping the autophagy active." (PMID 33925206, 2021). "Baicalin can also induce apoptosis in cancer cells by downregulating mTOR signaling pathways." (PMID 33768214, 2021). "The inhibition of mTOR by rapamycin and its analogs seems to be effective in cancer treatment." (PMID 34659408, 2021). "To date, 126 clinical trials are currently ongoing using Akt inhibitors (including 10 phase III trials) and 140 clinical trials (including 14 phase III) are currently being conducted on mTOR inhibitors either as monotherapy or as part of a combination therapy for many cancer types." (PMID 34500781, 2021). "Although there is scarce information regarding activation of signaling pathways in digestive cancer, recent papers show evidence for the involvement of at least two pathways in these cancers cells: the AKT/mTOR pathway on one hand, and the JAK/STAT pathway on the other hand." (PMID 33450887, 2021).
cancer (continued). "As a result, mTOR signaling is active in as many as 80% of human cancers." (PMID 34863080, 2021). "In addition, direct blockade of PD‐L1 within cancer cells has been reported to diminish glycolysis by inhibiting the mTOR pathway and the expression of glycolysis enzymes." (PMID 34363337, 2021). "Thus, in a stressful evolving microenvironment like that of a growing cancer, mTOR plays a critical role in controlling the metabolic responses." (PMID 34283054, 2021). "The highly conserved serine-threonine kinase mTOR is frequently activated in cancer." (PMID 34784907, 2021). "Further exploration indicated that erianin significantly reduced the expression of protein-palmitoyl thioesterase 1 (PPT1), a critical regulator of two key processes that drives cancer aggressiveness-autophagy and mammalian target of rapamycin (mTOR) signaling." (PMID 35004674, 2021). "mTOR activity is regulated by metabolic sensors as well as by numerous factors comprising the phosphatase and tensin homolog/PI3K/AKT canonical pathway, which are often mutated in cancer." (PMID 34634301, 2021). "Moreover, EGCG synergistically enhanced curcumin’s effects on cancer cells by inducing autophagy through suppression of the Akt/mTOR signaling pathway." (PMID 33768214, 2021). "Taken together, these data suggest that enhanced PI3K/Akt/mTOR signaling in cancer cells may affect T cells fate, and thereby influencing tumorigenesis and malignant progression." (PMID 35250965, 2021). "MTOR regulates cancer cell metabolism by controlling expression of the TFs c‐Myc and HIF1α." (PMID 34003553, 2021). "Therefore, the mTOR pathway is an attractive target for immunosuppressive and anti-proliferative therapies for patients after organ transplantation or suffering from cancer, respectively." (PMID 34206503, 2021). "According to the results of GSEA, the low-risk group had the negative correlations of the MTOR signaling pathway and autophagy in cancer (p<0.05)." (PMID 34414116, 2021). "Therefore, upregulation of the PI3K/AKT/mTOR pathway in cancer cells can reconfigure their metabolism through inappropriate overactivation of HIF-1, leading to generation of lactate from glycolysis in an oxygen-irrespective fashion." (PMID 34895222, 2021). "Synthetically, ropivacaine may regulate cell proliferation and apoptosis through the IGF-1 R/PI3K/AKT/mTOR axis to exert anti-cancer effects." (PMID 34696683, 2021). "Moreover, the availability of CDX-3379, the first HER3 blocking antibody that recognizes both human and mouse HER326 enabled us to investigate the direct impact of blocking HER3-PI3K/mTOR signaling in cancer cells on their TIME in syngeneic animal models." (PMID 33888713, 2021). "Since mTORC1 is hyperactivated in a large subset of cancers, the regulation of mTOR activity is a promising therapeutic target and, accordingly, several small molecules have been developed to inhibit its activity in various forms of cancer, including rapalogs and second-generation mTOR inhibitors." (PMID 33541283, 2021). "In this regard, targeting the mTOR pathway can be used as a potential therapeutic strategy in an attempt to modulate macrophage responses in the context of TME to promote antitumor immunity with therapeutic benefit in a broad range of cancers." (PMID 35250965, 2021). "Therefore, the PI3K/AKT/mTOR pathway is an important target for cancer treatment, and several inhibitors of this pathway have been developed." (PMID 34120414, 2021). "And the genes involved in the mTOR pathway were significantly altered in cancer cachectic muscles." (PMID 34175899, 2021). "Rapamycin inhibition of mTOR kinase sensitizes cancer cells to radiotherapy." (PMID 33640883, 2021). "Thus, targeting the signaling pathway of mTOR/AKT/PI3K was also a new strategy for the cancer treatment." (PMID 34840573, 2021).
cancer (continued). "Different mechanisms for hormonal resistance include loss of ER in the cancer cells, ER mutation, HER2 mutation, epigenetic alteration, and most importantly Phosphoinositide 3-kinase (PI3K)/AKT/mammalian target of rapamycin (mTOR) mTOR signaling pathway activation." (PMID 33670524, 2021). "According to these considerations, the energetic stress directly caused by metformin might provide a favorable therapeutic index in a sizable number of cancers, mostly in those characterized by an overexpression of mTOR." (PMID 34439897, 2021). "Indeed, other studies also indicated the involvement of the PI3K/AKT/mTOR signaling pathway in mediating the dormant state in multiple cancer models." (PMID 34832087, 2021). "We identified a total of 1423 mutations, 16 of which were nonsilent, likely pathogenic, and affecting known cancer genes or genes involved in mTOR signaling." (PMID 34255745, 2021). "The activation of the YAP and mTOR pathways is correlated in human cancer tissues." (PMID 34462427, 2021). "There have been reports that cancer can be targeted with inhibitors of the mTOR pathway." (PMID 34194607, 2021). "PI3K/AKT/MTOR pathway is one of the most commonly activated pathways in cancer." (PMID 35201498, 2021). "There is growing evidence that mTOR inhibitors in multi-drug combination regimens can overcome the largely cytostatic effect of mTOR inhibitor monotherapies thus leading to improved treatment outcomes especially in advanced cancers." (PMID 33935721, 2021). "Work must be continued to validate predictive biomarkers, which may help to identify the patients who will most likely benefit from treatment with mTOR inhibitors and allow for the better determination of rational combinations of anti-cancer agents." (PMID 33572326, 2021). "The PI3K/AKT/mTOR pathway dysregulation are often observed in human cancers." (PMID 34135756, 2021). "An increase in AKT, GSK-3β, mTOR, 70s 6 kinase was revealed in cancers with point mutation compared with the primary tumor without a mutation." (PMID 34319022, 2021). "It has been reported that the activation of the Akt/mTOR pathway could lead to the activation of STAT3 to participate in the maintenance of cancer stemness of NSCLC cells." (PMID 34681614, 2021). "Other important regulatory pathways upstream of autophagy, such as PI3K/AKT/mTOR, may play pivotal roles in the development of cancer." (PMID 33995620, 2021). "MTORC2 is responsible for cell survival and proliferation and MTORC2 activation has previously been shown for cancer-associated MTOR variants, but not, to our knowledge, for NDD-associated variants." (PMID 34197453, 2021). "As a result, progranulin depletion triggers cell death, it could solve the problem of resistance to mTOR inhibitor in cancer cells by upregulation of TGF-β production." (PMID 33490663, 2021). "AMPK/mTOR pathway is well known to be regulated cancer cell growth and survival." (PMID 34422646, 2021). "Evidence indicates that the mTOR signaling pathway governs cell growth and is activated in cancer." (PMID 33824874, 2021). "The role of PI3K/Akt/mTOR signaling pathway components in cancer." (PMID 35250965, 2021). "Moreover, PTX downregulated the expression of Akt and mTOR to inhibit cancer-related OS characteristics." (PMID 34584572, 2021). "mTOR facilitates cancer cell growth and proliferation by promoting glucose metabolism." (PMID 35250965, 2021). "Therefore, there is need for further investigation into the correlation between ferroptosis and anti-cancer mechanism of these mTOR inhibitors." (PMID 35082669, 2021). "In addition, the anti-cancer treatment can also be seen to reduce the expression of mTOR, p62, BCL2, and upregulated Beclin 1 and LC3-I/II, which are significant autophagy-related genes." (PMID 34681840, 2021). "Inhibitors that target the PI3K/AKT/mTOR cascade can improve overall cancer treatment." (PMID 34821587, 2021). "The dysregulation of mTOR pathway often leads to the initiation and progression of cancer." (PMID 33996789, 2021).
cancer (continued). "Furthermore, blocking programmed death ligand-1 (PD-L1) on cancer cells reduces their glycolysis rate by inhibition of mTOR-related pathways, which would permit T-cells to exploit their glycolytic capacity and restore IFN-γ production." (PMID 35070990, 2021). "mTOR is regulated by phosphatidylinositol 3-kinase/Akt pathway to participate in proliferation, angiogenesis and metastasis of CRC and inhibition of mTOR could emerge as a potential strategy for cancer intervention of CRC." (PMID 33347535, 2021). "β-caryophyllene has been found to hinder metastasis, cause a reduction in oncogene and protein expression of cancer cells while upregulating genes and proteins that destroy cancer cells through the modulation of pathways such as MAPK, PI3K, AKT, mTOR, S6K1, and STAT3." (PMID 35009027, 2021). "Somatic gain-of-function mutations in PIK3CA, determining a constitutive activation of the PI3K/AKT/mTOR pathway, are among the main driver mechanisms in cancer and are also responsible for benign overgrowth syndromes, collectively known as PIK3CA-related overgrowth spectrum (PROS) disorders." (PMID 34568242, 2021). "mTOR, which is frequently activated in cancer, controls cell growth and metabolism." (PMID 34540654, 2021). "The mTOR pathway is critical in regulating cell survival, metabolism, growth, and protein synthesis in response to upstream signals under both normal physiological and pathological conditions, particularly in cancer." (PMID 34361836, 2021). "The mTOR signaling pathway has been reported to be overactivated in most human cancers." (PMID 34194607, 2021). "PI3K/AKT/mTOR pathway is altered during the progression of various cancer types." (PMID 34843456, 2021). "For instance, mTOR/STAT3 is commonly dysregulated in various cancers." (PMID 33652661, 2021). "Indeed, PI3K/AKT/mTOR functions as a nutrient sensor to induce cancer cell proliferation and survival under nutrient replete conditions." (PMID 33807608, 2021). "Overexpression of mTOR is commonly observed in various types of cancers." (PMID 34279440, 2021). "Additionally, some studies showed reduced levels of phosphorylated Akt, phosphorylated mTOR and c-Myc, all of which are often upregulated in cancer." (PMID 33668434, 2021). "Several novel functions of the mTOR pathway in cancers have been discovered lately." (PMID 33996789, 2021). "We therefore sought to identify other targeted agents that might cooperate with mTOR inhibitors to enhance oxidative stress beyond threshold levels, thereby more effectively killing cancer cells." (PMID 33754064, 2021). "Thus, deregulated mTOR signaling in cancer can modulate the TME, thereby affecting the tumor immune microenvironment." (PMID 35250965, 2021). "mTOR-driven cancer progression can be inhibited by activation of AMPK73–75." (PMID 33824293, 2021). "Since activation of the mTOR signaling pathway is ubiquitous in cancers, therapeutic inhibition of mTOR using analogs of Rapamycin (‘Rapalogs’) has been an attractive strategy for systemic management of cancer, albeit with modest benefits." (PMID 33935721, 2021). "We then compared the mTOR pathway genes in normal and cancer tissues to determine whether they exist as risky or protective genes." (PMID 34194607, 2021). "Furthermore, the use of only mTOR inhibitor INK128 was sufficient to induce the entry of some cancer cells into the diapause-like dormant state, while withdrawing the treatment resulted in cell growth resumption." (PMID 34832087, 2021).